PPARG (peroxisome proliferator activated receptor gamma)
Diseases named in the same sentence as PPARG in open-access papers (continued):
Sharing a sentence is not in itself a finding about the gene and the disease.
atherosclerosis (continued). "Given the delicate balance between WNT and PPARγ in VC, this could be a double-edged sword, since a high activation of the WNT/β-catenin pathway, as found in atherosclerosis, could reduce PPARγ availability, shifting the balance towards a pathologically high β-catenin concentration." (PMID 33322009, 2020). "The upregulation of SOD1, CAT, MIF, and PPARγ observed in this study is in line with previous works, which have demonstrated the antioxidant proprieties of a diet rich in nuts, related to the regulation of cellular pathways of atherosclerosis, inflammation, and oxidative stress." (PMID 31354906, 2019). "As a member of a nuclear hormone superfamily, PPARγ plays essential roles in the occurrence and development of atherosclerosis, which might be due to its regulation of glycolipid metabolism, involvement in inflammation and activation of cholesterol efflux/reverse cholesterol transport." (PMID 29801502, 2018). "Studies suggest that PPARG modulates the expression of genes involved in energy storage and utilisation and plays a critical role in the regulation of adipocyte differentiation, lipogenesis, insulin resistance, inflammatory response, angiogenesis and atherosclerosis." (PMID 28727849, 2017). "In addition, there are multiple paths by which 9-HODES may be involved in the development of atherosclerosis and risk of CHD, including oxidized LDL, HDL metabolism and PPARγ action." (PMID 27330524, 2016). "Interestingly, Zhang and colleagues demonstrated that TNFα is capable to induce transcytosis of LDL at the first stages of atherosclerosis development through a mechanism dependent of nuclear factor kappa B (NF-κB) and peroxisome proliferator-activated receptor gamma (PPAR-γ) crosstalk." (PMID 26578976, 2015). "Activation of the nuclear hormone receptor, PPARγ, with pharmacological agonists promotes a contractile vascular smooth muscle cell phenotype and reduces oxidative stress and cell proliferation, particularly under pathological conditions including vascular injury, restenosis, and atherosclerosis." (PMID 26451838, 2015). "Several studies have demonstrated that the in vivo administration of PPARγ ligands inhibited adjuvant-induced arthritis, colitis, and atherosclerosis in animal models, raising the possibility that PPARγ might be a critical component of the inflammatory process." (PMID 24612634, 2014). "After extracted genes in lipid and atherosclerosis pathway, a new PPI was established, which was prompted that genes including AKT1, BCL-2, CAPS3 and PPARG would be the core genes worked." (PMID 41559682, 2026). "In conclusion, this study found that the important direct targets of hawthorn in atherosclerosis included IL1B, CTSD, HMOX1, and PPARG." (PMID 40824771, 2025). "In cardiovascular diseases, H2S-promoted Nrf2 nuclear translocation in concert with PPARγ and KATP channels ameliorates atherosclerosis and hypertension." (PMID 41192145, 2025). "Pretreatment with BMP4 abrogated PVAT induced upregulation of PPARγ, ABCA1 and ABCG1, further confirming the role of BMP4 in atherosclerosis." (PMID 39327610, 2024). "For diseases such as atherosclerosis, inflammation and hypertension, PPAR is considered an important therapeutic target; among them, PPARG plays an important role in regulating atherosclerosis." (PMID 38468335, 2024). "In atherosclerosis, the expression levels of CD36, PPARG, MMP9 and SRC were upregulated, while NOB inhibited their expression." (PMID 38468335, 2024). "The main mechanisms of chlorogenic acid in inhibiting atherosclerosis include increased synthesis and mRNA expression of PPARγ, LXRα, ABCA1 and ABCG1, as well as transcriptional activity resulting from PPARγ activation." (PMID 37432383, 2023). "In conclusion, the present study demonstrated that oridonin attenuated atherosclerosis by suppressing foam macrophage formation and inflammation through FABP4/PPARγ signalling pathway." (PMID 37905351, 2023).
atherosclerosis (continued). "In the results of advanced atherosclerosis mice, GLSP was able to downregulate fatty acid synthesis-related genes (FASN, PPARγ, SCD1) and upregulate fatty acid catabolism-related genes (HSL)." (PMID 36923537, 2023). "We demonstrate that SFN can play a preventive role in macrophage foam cell formation and atherosclerosis through restraining cholesterol uptake and inducing efflux via the potential modulation of the expression of CD36, ABCA1/G1, PPARγ and Nrf2/HO-1." (PMID 37432260, 2023). "PPI network and GO/KEGG pathway enrichment analysis showed that AO toxic compounds mainly targeted PPARG and TNF and regulated the lipid and atherosclerosis signaling pathway." (PMID 36457705, 2022). "Previous studies have demonstrated a crucial role for PPARγ in the induction of ABCA1/ ABCG1 expression, and the prevention of foam cell formation and atherosclerosis progression." (PMID 35590369, 2022). "In atherosclerosis, PPARγ is reported to bind with the promoter region of CD36, and the PPARγ agonist BLR49653 strongly induces CD36 expression." (PMID 35432274, 2022). "Quercetin prevents the development of atherosclerosis in ApoE−/− mice by regulating the expression of PCSK9, CD36, PPARγ, LXRα, and ABCA1." (PMID 35845584, 2022). "We have demonstrated the dueling relationship between PPARγ and PPARα in terms of macrophage differentiation, bacterial and viral clearance, IBD, and atherosclerosis." (PMID 35003101, 2021). "Collectively, these findings reveal that PAK1 is an independent effector of macrophage polarization at least partially attributed to regulation of PPARγ expression, which suggested PAK1-PPARγ axis as a novel therapeutic strategy in atherosclerosis management." (PMID 34603600, 2021). "OxLDL is a ligand for PPARγ and upregulates the expression of CD36, favoring the uptake of OxLDL to macrophages and consequently contributing to the development of atherosclerosis through immune system activation." (PMID 34204618, 2021). "We believe that the activity of PPARγ is probably modified by environmental factors, such as HFCD, and the upregulation of PPARγ stimulates reverse cholesterol transport to prevent atherosclerosis." (PMID 33261070, 2020). "Activation of the PPARγ/LXRα signaling pathway has been shown to increase ABCA1 and ABCG1 expression and thereby mitigate atherosclerosis." (PMID 33959213, 2020). "Our results revealed that HMGB1 is a critical signal for TLR4-mediated the down-regulation of PPARγ/LXRα-ABCA1, which accelerates CUMS-induced atherosclerosis." (PMID 30881312, 2019). "Consequently, the PPARγ/AMPK/eNOS pathway could be a target for the treatment of atherosclerosis." (PMID 31354915, 2019). "Blocking HMGB1 release by EP or inhibiting TLR4 activation by TAK-242 almost reversed CUMS-induced the drownregulation of PPARγ-LXRα-ABCA1 and impeded the development of atherosclerosis in apoE-/- mice." (PMID 30881312, 2019). "Our study demonstrates that HMGB1 promotes CUMS-induced atherosclerosis via activating TLR4 signaling, which drownregulates the expression of PPARγ-LXRα-ABCA1." (PMID 30881312, 2019). "PPARγ activates the PON1 gene, increasing synthesis and release of PON1 from the liver and reducing atherosclerosis." (PMID 31252610, 2019). "In atherosclerosis, ox-LDL binding to CD36 results in a positive feedback loop via activation of peroxisome proliferator activated receptor gamma (PPARγ)." (PMID 29896109, 2018). "Phospho-AKT modulates PPARγ/LXR driven gene expression of which ABCA1 is a prominent target with well-documented roles in lipid metabolism and atherosclerosis." (PMID 29144234, 2017).
atherosclerosis (continued). "Consistent with the role of PPARγ in inflammation and immunity, TZD treatment is known to be protective against complications such as atherosclerosis and renal disease in various murine SLE models." (PMID 28182703, 2017). "H2S has been reported to hamper the progression of atherosclerosis in fat-fed ApoE−/− mice and down-regulate CX3CR1 and CX3CL1 expression by modulating PPARγ in macrophages and lesion plaques." (PMID 27136542, 2016). "The clarification of PPARγ/AMPK/eNOS pathway would help to find the therapeutic targets for the treatment of endothelial injury and atherosclerosis." (PMID 25388834, 2015). "PPARγ is also closely clustered with P8, PPARβ, and ABCG1 which are well-known for their roles in atherosclerosis." (PMID 18237428, 2008). "Although suggested in our study as LEAD-specific, the regulatory crosstalk between PPARG and the VEGF and TGF-beta signaling pathways has been described in earlier studies, its precise regulatory role in atherosclerosis development requires further investigation." (PMID 41009355, 2025). "KTRI for hawthorns in the PVAT microenvironment of atherosclerosis were CTSD, PPARG, and HMOX1." (PMID 40824771, 2025). "KTRI for hawthorn in the PVAT microenvironment of atherosclerosis were CTSD, PPARG, and Hmox1." (PMID 40824771, 2025). "It is suggested that early in the development of atherosclerosis, macrophage-derived 13-HODE, at lower concentrations, plays a protective role, enhancing the removal of lipids and cellular debris from the arterial wall through PPARγ activation." (PMID 41441285, 2025). "Furthermore, it has been shown that PPARγ augments ABCA1/G1 and SR-B1 expression to inhibit MDFC formation and exert an anti-atherosclerosis effect." (PMID 40867523, 2025). "In addition to activating PPARα signaling, many TCM prescriptions stimulate PPARγ–liver X receptor (LXR) α–ABCA1/ABCG1 signaling pathways, thereby ameliorating lipid profiles and atherosclerosis through upregulation of reverse cholesterol transport (RCT)." (PMID 38699583, 2024). "Importantly, these exosomes demonstrate a regulatory role in NRs such as PPARα, PPARγ, PPARδ, RORα, ERα, and ERβ, across a range of chronic diseases, including AIDS, atherosclerosis, cancer, CRS, diabetes, NASH, neurological diseases and obesity." (PMID 39327610, 2024). "In addition to its role in lipid metabolism and inflammation, PPARγ is also closely related to CD36, a core gene among the marker genes we are currently investigating, further underscoring its significance in atherosclerosis." (PMID 39660117, 2024). "Furthermore, 5-aminolevulinic acid-mediated sonodynamic therapy improves cholesterol efflux via activating PPARγ–LXRα–ABCA1/ABCG1 signaling pathways, enhancing efferocytosis and cholesterol efflux, and eventually ameliorating atherosclerosis." (PMID 38699583, 2024). "However, genistein reverses Ang II-induced downregulation of PPARγ to inhibit the expression of CRP and matrix metalloproteinase 9 in vascular smooth muscle cells (VSMCs), thereby reducing inflammatory responses in atherosclerosis." (PMID 38699583, 2024). "DeSUMOylation of PPARγ may inhibit neointimal formation and reduce vascular SMC proliferation, suggesting that it confers protection from atherosclerosis." (PMID 37833942, 2023). "The purpose of this study is to investigate whether SFN treatment could influence macrophage foam cell formation and atherosclerosis and explore the potential mechanistic contribution of CD36, ABCA1/G1 expression and the involvement of PPARγ and Nrf2." (PMID 37432260, 2023). "Although many studies have examined endothelial cell disorders in atherosclerosis, the role of PPARγ in endothelial dysfunction is still not well understood." (PMID 37833942, 2023). "Further studies using transgenic mouse models with PPARγ SUMOylation or deSUMOylation may provide additional evidence of this PTM’s role in regulating EC function and atherosclerosis development." (PMID 37833942, 2023).
atherosclerosis (continued). "Taken together, oridonin might have potential to protect against atherosclerosis by modulating the formation and inflammatory response in foam macrophages through FABP4/PPARγ signalling." (PMID 37905351, 2023). "Deacetylation of PPARγ inhibits the cholesterol efflux PPARγ/LXRα/ABCA1 pathway, increased production of proinflammatory M1 macrophages and promotes the development of inflammatory response, leading to the onset and development of atherosclerosis." (PMID 35309069, 2022). "Consistent with this explanation, we confirmed the markers related to dyslipidemia (e.g., PPARγ and leptin) in oleic and palmitic acid (OAPA) and lipopolysaccharide (LPS) treated-HUVECs for mimicking atherosclerosis of artery as well as ABCA1 and its target miRNAs." (PMID 34440128, 2021). "Studies in the atherogenic mice models showed that the activation of the peroxisome proliferator-activated receptor-gamma (PPAR-γ) pathway or treatment with IL-13 induces M2 macrophage polarization, increases the plaque collagen content, and inhibits the progress of atherosclerosis." (PMID 33379334, 2020). "The activation of PPARγ signaling demonstrated immunomodulatory properties in macrophages; thus, deciphering the interplay between PPARγ and WNT signaling in atherosclerosis may improve our understanding of VC." (PMID 33322009, 2020). "We conclude that Rg3 may protect endothelial cells and inhibit atherosclerosis by up-regulating PPARγ via repressing FAK-mediated pathways, indicating that Rg3 have good potential in preventing dyslipidemia induced atherosclerosis." (PMID 32390845, 2020). "Thiazolidinediones (TZDs) induced PPARγ activation also reduced the expression of inflammatory factors, including TNF-α and gelatinase B, in the aortic root, thus inhibiting the development of atherosclerosis." (PMID 29690611, 2018). "PPARγ is highly expressed in the vascular system, where it is involved in the repression or expression of certain genes such as angiotensin type 1 receptor (AT1R), which can prevent or ameliorate endothelial dysfunction and atherosclerosis." (PMID 27313601, 2016). "In another investigation by Zhong Q and colleagues, high density lipoprotein increased oxidized low density lipoprotein (LDL) uptake of inflammatory adipocytes via upregulation of PPARγ/CD36 pathway, which may be a new mechanism of anti-atherosclerosis." (PMID 26036798, 2015). "In addition, by inferring PCL-responsive gene networks in early, mature and advanced atherosclerotic lesions, we identified key drivers specific for regression of early (PPARG), mature (MLL5) and advanced (SRSF10/XRN2) atherosclerosis." (PMID 24586211, 2014). "PPARγ agonists can inhibit these effects of ANG II by suppression of the ANG II-induced signaling pathway, which suggests that PPARγ agonists have beneficial effects against atherosclerosis and restenosis." (PMID 21269478, 2011). "This can be explained, in part, by the fact that PPARγ agonist stimulate expression of the scavenger receptor CD36 in macrophages that facilitates uptake of oxidized LDL and contributes to the development of atherosclerosis." (PMID 18485218, 2008). "PPARγ agonists of the thiazolidinedione class have been reported to inhibit TGFβ signaling, CTGF expression and fibrosis, and they also can reduce atherosclerosis." (PMID 17505534, 2007). "Furthermore, crocetin (CRO) has been reported to downregulate total cholesterol (TC) and cholesterol esters (CE), effectively limiting lipid droplet formation and activating PPARγ/LXR-α to facilitate reverse cholesterol transport, thereby ameliorating atherosclerosis." (PMID 40099271, 2025). "This reveals that PPARG and MT1X may be beneficial genes for atherosclerosis." (PMID 40824771, 2025).
atherosclerosis (continued). "Ganoderic acid A (GAA) prevents ox-LDL-induced macrophage inflammation and lipid deposition in THP-1 cells by blocking Notch1/PPARγ/CD36 signaling, which may provide a theoretical framework for the clinical application of GAA in the treatment of atherosclerosis." (PMID 40099271, 2025). "Our results showed that oridonin inhibited atherosclerosis, as it performed double duty on lipid modulation and anti‐inflammation properties in macrophages via fatty acid binding protein 4 (FABP4)/peroxisome proliferator‐activated receptor gamma (PPARγ) pathway." (PMID 37905351, 2023). "The lack of PPARγ increased atherosclerosis formation in a mouse model." (PMID 35682840, 2022). "In addition, HFD with linseed oil did not decrease the LDL/VLDL level, which is consistent with a previous report showing that PPARγ agonist, rosiglitazone, inhibited the development of atherosclerosis without affecting serum cholesterol level." (PMID 34001916, 2021). "Moreover, in patients with atherosclerosis, peroxidation products produced in the vascular wall promote adiponectin gene expression in PVAT through a peroxisome proliferator-activated receptor-γ (PPARγ)-dependent mechanism." (PMID 33391033, 2020). "Further studies might be needed to examine the involvement of other signaling pathways such as STAT, PPARγ, CREB, and IRFs in macrophage polarization and inflammation, as well as other mechanisms, such as oxidative stress and autophagy, in LMP10-mediated atherosclerosis in this model." (PMID 33195259, 2020). "In addition, PPARγ antagonist GW9662 co-administration mostly blocked these effects, suggesting the important role of PPARγ pathways in mediating 20(S)-Rg3 effects in macrophage polarization and atherosclerosis progression." (PMID 29867472, 2018). "Peroxisome proliferator-activated receptor gamma (PPARG, also known as NR1C3), a member of the nuclear hormone receptor subfamily, regulates the expression of a network of genes involved in adipogenesis and lipogenesis, insulin sensitivity, inflammation and atherosclerosis." (PMID 28727849, 2017). "However, the effect of PPARγ agonists on endoplasmic reticulum (ER) stress that plays an important role in the progression of atherosclerosis has not been determined." (PMID 26061913, 2015). "Importantly, while activation of PPARγ inhibits the development of atherosclerosis, regression of atherosclerosis is not induced, which is in contrast to the regression seen with CLA supplementation." (PMID 23964012, 2013). "Because high LDL-cholesterol levels show strong correlation with atherosclerosis, it was proposed the uptake of oxidized LDL by monocytes and the subsequent activation of PPARγ might contribute to the appearance of foam cells, the early hallmarks of atherosclerotic lesions." (PMID 21382489, 2011). "Treatment of smLRP1− animals with the PPARγ agonist rosiglitazone abolished nuclear pSmad accumulation, reversed the Marfan-like phenotype, and markedly reduced smooth muscle proliferation, fibrosis and atherosclerosis independent of plasma cholesterol levels." (PMID 17505534, 2007). "We therefore decided to test, whether activation of PPARγ by rosiglitazone, a compound of this class that is in clinical use, might result in reduced nuclear accumulation of pSmad2 and suppression of atherosclerosis in mice lacking LRP1." (PMID 17505534, 2007). "Besides, these components may play a role in increasing the expression of sterol regulatory peroxisome proliferator-activated receptor gamma (PPARγ) and element-binding protein (SREBP)-2 which could ultimately lead to alleviation of atherosclerosis progression." (PMID 34742318, 2021).